PROP1 (PROP paired-like homeobox 1)
Description:
Possibly involved in the ontogenesis of pituitary gonadotropes, as well as somatotropes, lactotropes and caudomedial thyrotropes.
Synonyms: PROP-1; CPHD2
Tractability: No criterion of Open Targets' tractability assessment is met for any kind of drug.
Gene: Protein-coding gene on chromosome 5 (177,992,235 to 177,996,242, reverse strand). Ensembl gene ENSG00000175325.
Subcellular location: Nucleus
Gene Ontology:
Molecular function: protein binding; sequence-specific double-stranded DNA binding; DNA-binding transcription factor activity, RNA polymerase II-specific; RNA polymerase II cis-regulatory region sequence-specific DNA binding; beta-catenin binding; chromatin binding; DNA binding; DNA-binding transcription activator activity, RNA polymerase II-specific; DNA-binding transcription repressor activity, RNA polymerase II-specific
Biological process: central nervous system development; regulation of transcription by RNA polymerase II; negative regulation of transcription by RNA polymerase II; nervous system development; pituitary gland development; positive regulation of transcription by RNA polymerase II; regulation of DNA-templated transcription
Cellular component: chromatin; transcription regulator complex; nucleus
Genetic constraint (gnomAD): Loss-of-function variants: 12 observed, 22.35 expected, observed/expected ratio (o/e) 0.54, 90% interval 0.34 to 0.87. The upper end of that interval is the gene's LOEUF score, 0.87, which puts it in group 3 of 6, group 1 being the genes least tolerant of losing a copy. Missense variants: 275 observed, 292.15 expected, observed/expected ratio (o/e) 0.94, 90% interval 0.85 to 1.04. Synonymous variants: 111 observed, 117.11 expected, observed/expected ratio (o/e) 0.95, 90% interval 0.81 to 1.11.
Homologues: Orthologues: chimpanzee PROP1 (98% identical), macaque PROP1 (90% identical), pig PROP1 (81% identical), dog PROP1 (79% identical), rabbit PROP1 (77% identical), mouse Prop1 (73% identical), guinea pig PROP1 (72% identical), rat Prop1 (70% identical). Paralogues in human: ESX1 (30% identical), ARX (30% identical), RAX (30% identical), ALX4 (29% identical), PAX7 (29% identical), MIXL1 (28% identical), PAX3 (27% identical), VSX2 (27% identical), PAX6 (26% identical), ALX3 (25% identical), PRRX1 (25% identical), SEBOX (25% identical), and 38 more.
Diseases named in the same sentence as PROP1 in open-access papers:
PROP1 is named in the same sentence as 41 diseases in open-access papers, as found by Europe PMC text mining. Sharing a sentence is not in itself a finding about the gene and the disease. The quoted sentences say what the papers report.
pituitary hormone deficiency (35 papers, 2009 to 2025). "The most common disease-causing gene for combined pituitary hormone deficiency (CPHD) is PROP1 (Prop paired-like homeobox 1), accounting for up to 55% of CPHD cases." (PMID 40141050, 2025). "The most commonly identified genetic cause of combined pituitary hormone deficiency (CPHD) is PROP1 gene mutations." (PMID 38147295, 2024). "In particular, combined pituitary hormone deficiency caused by mutations in the PROP1 gene is associated with decreased TSH secretion." (PMID 39728398, 2024). "Various studies have described PROP1 gene variants as responsible for causing combined pituitary hormone deficiency." (PMID 32982993, 2020). "Additional pituitary deficits also arise over time in monogenic hypopituitarism caused by mutations in PROP1, POU1F1, HESX1, and other developmental genes." (PMID 33140249, 2020). "ACTH deficiency has been described in patients with hypopituitarism caused by PROP1, POU1F1, LHX3, LHX4, and GLI2 mutations." (PMID 33140249, 2020). "At birth, in contrast to patients with congenital CPHD caused by other etiologies, neonates with PROP1 defects lack perinatal signs of hypopituitarism." (PMID 31090814, 2019). "The first description of patients with combined pituitary hormone deficiencies (CPHD) caused by PROP1 mutations was made 20 years ago." (PMID 31090814, 2019). "It has been 20 years since Wei Wu in M.G. Rosenfeld’s Research Unit first identified inactivating mutations of the PROP1 gene in humans with combined pituitary hormone deficiency (CPHD)." (PMID 31090814, 2019). "In order to make an overview of PROP1 mutation frequencies according to country of origin, we performed a pubmed search using ‘PROP1 AND mutation AND combined pituitary hormone deficiency’ (filter: English)." (PMID 29255988, 2018). "Pituitary-specific paired-like homeodomain transcription factor, PROP1, is associated with multiple pituitary hormone deficiency." (PMID 30112224, 2018). "Mutations in PROP1 are the most common cause of hypopituitarism in humans; therefore, unraveling its mechanism of action is highly relevant from a therapeutic perspective." (PMID 27351100, 2016). "PROP1 gene mutations lead to hypopituitarism that is characterised by insufficiency of growth hormone (GH), luteinising hormone (LH), follicle-stimulating hormone (FSH) and thyroid-stimulating hormone (TSH) synthesis and release." (PMID 26608600, 2016). "Most institutions start with analysis of the PROP1 gene in cases of combined pituitary hormone deficiency." (PMID 26757742, 2016). "The presence of mutations in PROP1, the most common genetic cause of combined pituitary hormone deficiency (CPHD) associated with short stature, was excluded." (PMID 26323392, 2015). "Genetic background affects the viability of young Prop1 deficient mice, largely due to different responses of target organs to pituitary hormone deficiency." (PMID 22145038, 2011). "Mutations in the Prop1 gene cause hypopituitarism due to Combined Pituitary Hormone Deficiency (CPHD) in humans and the Ames dwarfism in mice." (PMID 19283075, 2009). "Patients carrying mutations in the POU1F1 or PROP1 genes may present with this disorder, making it necessary to differentiate child-onset hypopituitarism from pediatric hypophysitis and pituitary hyperplasia." (PMID 41465179, 2025). "GH gene expression is controlled, among others, by the pituitary-specific transcription factors POU class 1 homeobox 1 (POU1F1) and PROP paired-like homeobox 1 (PROP1), which are also implicated in adenohypophysis development and associated with hypopituitarism." (PMID 34680948, 2021). "In patients with combined pituitary hormone deficiencies, the most frequently identified mutations were in PROP1 (11.6% of patients), followed by LHX3 (1.2%), whereas the gene mutations in patients with isolated GH deficiency were most frequently found in GH1 (4.8%), and GHRHR (1.1%)." (PMID 31555216, 2019).
pituitary hormone deficiency (continued). "PROP1 is important for the development of gonadotropin-secreting cells, and autosomal recessive mutations in this gene are the most common cause of combined pituitary hormone deficiency in humans." (PMID 31220230, 2019). "Prop1 encodes a paired-like homeodomain transcription factor, and is a heritable responsive gene for the combined pituitary hormone deficiency in the Ames dwarf mice (Prop1-deficient dwarf mice) and human patients showing absence or low levels of GH, PRL, TSH, LH and FSH, as well as ACTH." (PMID 21815952, 2011). "Interestingly, the pituitary deficiency induced by Prop1 mutations is reminiscent of the hypopituitarism induced by inactivation of the cell cycle regulator Cdk4." (PMID 19283075, 2009). "This study establishes the mechanism of PROP1 action in pituitary progenitor cells, offers new candidate genes for cases of pituitary hormone deficiency with unknown etiology, and lays the foundation for investigating the role of EMT in pituitary tumor formation." (PMID 27351100, 2016). "There are many causative genes for its isolated form or for multihormonal hypopituitarism, such as TSHβ, TRHR, TBL1X and IRS4 (for heritable isolated central hypothyroidism) and PROP1, HESX1, SOX3 (for multihormonal hypopituitarism)." (PMID 39997750, 2025). "Postnatally, Prop1:Cre;BrafV600E/+;RosaTM/+ (Prop1:Cre;BrafV600E/+ thereafter) pups showed clear signs of severe hypopituitarism with dwarfism and growth failure, and they died prematurely around weaning compared to their Wt littermates." (PMID 33795686, 2021). "PROP-1, POU1F1, and HEX1 gene mutations were present in Turkish families with combined pituitary hormone deficiency." (PMID 32283895, 2020). "For PROP1, POU1F1, and HESX1, mutation frequencies are <10% in patients with sporadic combined pituitary hormone deficiency in Western Europe, although much higher in Eastern Europe." (PMID 31555216, 2019). "Mutation frequencies of PROP1, POU1F1 and HESX1 in patients with combined pituitary hormone deficiencies (CPHD) vary substantially between populations." (PMID 29255988, 2018). "This in-depth molecular analysis of PROP1 action advances our fundamental understanding of pituitary organogenesis and the pathophysiology of hypopituitarism." (PMID 27351100, 2016). "Mutations in several transcription factors, including HESX1, PROP1 and POU1F1 cause pituitary hormone deficiency in mice and humans." (PMID 27351100, 2016). "Mutations in several genes are known to cause hypopituitarism in children, and the pituitary transcription factors HESX1, PROP1 and POU1F1 (PIT1) are among them." (PMID 27351100, 2016). "Patients with mutations in transcription factors (eg PROP1, HESX1, SOX3) require long-term surveillance for evolving ACTH and other pituitary hormone deficiencies." (PMID 26416826, 2015). "Multiple pituitary hormone deficiency (MPHD) results from a variety of transcription factor mutations, including mutations in PROP1, POU1F1 (PIT1), HESX1, LHX3, LHX4, OTX2, SOX2, SOX3, and GLI2." (PMID 22145038, 2011). "Similar phenotype have the patients affected by Combined Pituitary Hormone Deficiency (CPHD), a hypopituitarism caused by mutations in Prop1 where there pituitary undergo progressive hormone loss suggesting a depletion of progenitors." (PMID 19283075, 2009). "Together, our results demonstrate that expression of oncogenic BrafV600E in developing progenitors (Prop1+ve cells) results in severe postnatal hypopituitarism due to a lack in terminal differentiation of TSH, LH and FSH and severe reduction of GH hormone-secreting cells." (PMID 33795686, 2021). "The early postnatal death of our Prop1:Cre;BrafV600E/+ mutant mice at around weaning may be attributed to severe hypopituitarism with complete lack of TSH." (PMID 33795686, 2021).
pituitary hormone deficiency (continued). "Interestingly, although little boy with combined pituitary hormone deficiency has adrenocorticotropic hormone (ACTH) deficiency, his elder sisters with the same gross PROP1 deletion have no ACTH deficiency." (PMID 30112224, 2018).
dwarfism (3 papers, 2011 to 2024). "Mice with genetically determined dwarfism (GH, GHR, GHRHR, PROP1 mutations that suppress the GH/IGF1 axis) are well known for their increased lifespan, and there is a number of studies in which such mice were fed with calorie-restricted diets." (PMID 39159129, 2024). "The loss of function mutations in PROP1 and PIT1 genes of long-lived Ames and Snell mice cause delayed growth and dwarfism." (PMID 39159129, 2024).
pituitary tumor (3 papers, 2016 to 2024). A benign or malignant neoplasm affecting the pituitary gland. "Transgenic overexpression of the pituitary stem cell marker PROP1 under control of the αGSU promoter also leads (after 1 year) to pituitary tumors including non-hormonal, GH-, PRL-, GH/PRL-, PRL/αGSU-, and TSH-producing adenomas." (PMID 29255445, 2017).
secondary hypothyroidism (3 papers, 2016 to 2024). "Although CH screening is primarily aimed at primary hypothyroidism, testing for PROP1 gene mutations may reveal some undetected cases of secondary hypothyroidism." (PMID 39728398, 2024).
adenoma (2 papers, 2017 to 2024). A neoplasm arising from the epithelium. "It has been determined that the MEG3 gene acts as a suppressor of adenoma development and is exclusively present in normal pituitary tissue (OMIM 605636), whereas the PROP1 gene is detected in adenomas (OMIM 601538)." (PMID 39022728, 2024). "PROP1 overexpression was not a feature of the adenomas but was detected in the non-neoplastic regions surrounding them, again suggesting a paracrine tumor-stimulatory role of the mutant (stem/progenitor) cells." (PMID 29255445, 2017).
central congenital hypothyroidism (2 papers, 2015 to 2024). Central or secondary congenital hypothyroidism is a type of permanent congenital hypothyroidism characterized by permanent thyroid hormone deficiency that is present from birth and secondary to a disorder in the thyroid-stimulating hormone (TSH) - thyrotropin-releasing hormone (TRH) system. "In addition, central congenital hypothyroidism is strongly associated with variants in the PROP1 gene, which is usually associated with pituitary hormone underproduction." (PMID 39728398, 2024).
Gonadotropin deficiency (2 papers, 2015 to 2021). A reduced ability to secrete gonadotropins, which are protein hormones secreted by gonadotrope cells of the anterior pituitary gland, including the hormones follitropin (FSH) and luteinizing hormone (LH). "Development of a PROP1 mutation early on in life leads to gonadotropin deficiency, which in turn leads to cryptorchidism, impaired sexual maturation, and infertility." (PMID 34948037, 2021). "HESX1, GLI2, and SOX3 mutations have been linked to hypopituitarism, and mutations in SOX2, LHX3, LHX4, and PROP1 may cause gonadotropin deficiency." (PMID 34948037, 2021). "The PROP1 gene was thus sequenced in order to detect a gene defect elsewhere that could explain the GH and gonadotropin deficiency, but no mutation was identified." (PMID 26323392, 2015). "A PROP1 mutation should be considered when a patient is observed to have GH, TSH, prolactin, and gonadotropins deficiency, especially in the absence of overt pituitary or posterior pituitary lesions on MRI, or in the case of intracranial pseudo-tumor." (PMID 34948037, 2021).
hypophysitis (2 papers, 2024 to 2025). Inflammation of the pituitary gland. "Prolactin deficiency accompanies several congenital syndromes due to mutations in PROP1 and Pit1/ POU1F and in X-linked IGSF1 deficiency syndrome, and several aqcuired conditions including Sheehan syndrome, IgG4-related hypophysitis, and immune checkpoint-inhibitor-induced hypophysitis." (PMID 39356415, 2024).
pituitary adenomas (2 papers, 2024 to 2025). "Gain of function gene mutations of PROP-1, which lead to aberrant constitutive expression of PROP-1 protein, delay the terminal dedifferentiation of gonadotrophs, induces pituitary adenomas, and causes the formation of RCCs." (PMID 39939491, 2025). "On the other hand, the overexpression of the PROP1 gene was observed in pituitary adenomas which indicates its crucial role in pituitary development." (PMID 38978053, 2024).
pituitary deficiencies (2 papers, 2009 to 2024). "The Hanhart's dwarfs on the island of Krk, as they have been called, have recessively inherited multiple pituitary deficiencies (MPHD) due to a mutation in a pituitary transcription factor gene, the PROP1 gene." (PMID 39189941, 2024).
Sheehan Syndrome (2 papers, 2024). "The most evident clinical manifestation of hypoprolactinemia is the failure of lactation after delivery (puerperal alactogenesis), as typically seen in women with Sheehan Syndrome, PROP-1 mutations or isolated PRL deficiency." (PMID 39172174, 2024).
Adrenal insufficiency (1 paper, 2024). Insufficient production of steroid hormones (primarily cortisol) by the adrenal glands. "The most interesting phenomenon in patients with the PROP1 mutation is the occurrence of secondary adrenal insufficiency." (PMID 38147295, 2024).
brain injuries (1 paper, 2021). "In turn, mutations of other transcription factors (e.g., PIT-1/POU1F1, PROP-1, LHX3, SOX2, SOX3, OTX2 and HESX1) lead to congenital MPHD, while hypothalamic-pituitary tumours (e.g., craniopharyngiomas), their treatment regimens or traumatic brain injuries result in acquired MPHD." (PMID 34445772, 2021).
breast carcinoma (1 paper, 2022). "The patient with PROP1 mutation in her family had an occurrence of multiple malignancies such as breast cancer, melanoma and lung cancers while the mother of the patient with KS suffered from breast cancer." (PMID 37435457, 2022).
colonic neoplasm (1 paper, 2019). A benign or malignant neoplasm that affects the colon.
congenital hypopituitarism (1 paper, 2024). "Patients with the PROP1 mutations present a clinical picture significantly different from that of other forms of congenital hypopituitarism." (PMID 38147295, 2024).
hypocortisolism (1 paper, 2011). "If ACTH deficiency were detected, then the mice would correspond to the findings of acquired hypocortisolism in human MPHD patients with lesions in the PROP1 gene." (PMID 22145038, 2011). "The main goal of this research was to study the pituitary-adrenal axis in two different mutant Prop1 alleles on different genetic backgrounds to detect any evidence of ACTH deficiency and subsequent hypocortisolism." (PMID 22145038, 2011).
Hypoglycemia (1 paper, 2011). A decreased concentration of glucose in the blood. "It is possible that severe hypoglycemia contributes to the increased susceptibility of Prop1 mutants to lethality on the B6 background, although other differences in metabolism may be responsible." (PMID 22145038, 2011).
prolactinoma (1 paper, 2022). "The latency period before the diagnosis of prolactinoma for the male patient with KS was 25 years, while for the female patient with PROP1 mutation was 10 years." (PMID 37435457, 2022).
cancer (3 papers, 2017 to 2023). A tumor composed of atypical neoplastic, often pleomorphic cells that invade other tissues. "Age-associated changes in DNA methylation are suppressed by genetic, dietary and drug interventions that extend lifespan and delay/suppress the incidence of cancer, specifically the Prop1 mutation in the Ames dwarf mouse, CR and rapamycin." (PMID 28351383, 2017).
genetic disorders (3 papers, 2017 to 2024). "Like other recessive genetic disorders, the frequency of PROP1 mutations is also higher in patients born to consanguineous parents." (PMID 31090814, 2019).
PROP1 also shares sentences with these, for which no sentence is quoted: hypogonadism (2 papers); hypogonadotropic hypogonadism (2); autosomal recessive disease (1); Central hypothyroidism (1); congenital hypogonadotropic hypogonadism (1); craniopharyngioma (1); female infertility (1); hypospadias (1); Infertility (1); Insulin resistance (1); liver cancer (1); MEGDEL syndrome (1); Micropenis (1); Miller syndrome (1); Obesity (1); Osteopenia (1); panhypopituitarism (1); pituitary stalk interruption syndrome (1); Primary hypothyroidism (1); tumor (1).